RNU6-278P (RNA, U6 small nuclear 278, pseudogene)
Gene: Small nuclear RNA gene on chromosome 20 (13,973,316 to 13,973,424, reverse strand). Ensembl gene ENSG00000212247.
Homologues: Orthologues: chimpanzee U6 (99% identical), macaque U6 (91% identical), guinea pig U6 (74% identical), rabbit U6 (73% identical), pig U6 (70% identical), dog U6 (69% identical), dog U6 (65% identical). Paralogues in human: RNU6-15P (76% identical), RNU6-420P (76% identical), RNU6-1042P (75% identical), RNU6-1263P (75% identical), RNU6-199P (75% identical), RNU6-21P (75% identical), RNU6-33P (75% identical), RNU6-39P (75% identical), RNU6-463P (75% identical), RNU6-468P (75% identical), RNU6-1 (74% identical), RNU6-1011P (74% identical), and 1288 more.